SMAD2 (SMAD family member 2)
Diseases named in the same sentence as SMAD2 in open-access papers (continued):
Sharing a sentence is not in itself a finding about the gene and the disease.
pulmonary hypertension (13 papers, 2016 to 2025). Increased pressure within the pulmonary circulation due to lung or heart disorder. "A prior study has demonstrated that miR-21 influences pulmonary hypertension via the TGF-β1/Smad2 pathway." (PMID 39309603, 2024). "Notably, high expression of TGFβ1 and phosphorylation of SMAD2/3 in the rat pulmonary hypertension model were reversed by eIF3a knockdown, and the expression of these proteins was also significantly greater in the AAV1-shRNA-NC group than in the control group." (PMID 40346622, 2025). "Furthermore, in the rat model of high pulmonary blood flow-induced pulmonary hypertension by surgical systemic-pulmonary shunting, the activated TGF-β1/Smad2/3 pathway could be inhibited by the administration of SO2 derivatives." (PMID 27721913, 2016).
nasopharyngeal carcinoma (11 papers, 2012 to 2024). A carcinoma arising from the nasopharyngeal epithelium. "Of late, TROY was confirmed as a susceptibility gene for nasopharyngeal cancer and lung cancer, and TROY can bind to TGFβ receptor I and block TGFβ downstream signal Smad2/3, thereby promoting tumor growth in nasopharyngeal cancer." (PMID 35646083, 2022). "SMAD2 is a member of mitotic checkpoints, and contributes to chromosomal instability in nasopharyngeal carcinoma." (PMID 30216655, 2018). "In addition, NDRG1 also upregulated E-cadherin expression by inhibiting the Smad2 pathway in nasopharyngeal cancer cells." (PMID 36293154, 2022). "Another possibility is the upregulating of SMAD2/3 by INHBA, as described in nasopharyngeal carcinoma and pancreatic ductal adenocarcinoma." (PMID 38329386, 2024). "Detection of miRNA expression profiles in different clinical stages of nasopharyngeal carcinoma (NPC) and NPC lymph node metastasis shows that the expression of miR-149 is upregulated in NPC and expression of its target gene, Smad2, is decreased with the progression of NPC." (PMID 23144691, 2012). "Additionally, SMAD2 directly binds to the lncRNA MACC1-AS1 promoter and thus increases MACC1-AS1 expression in nasopharyngeal carcinoma." (PMID 32923393, 2020). "INHBB reduces the phosphorylation of Smad2/3 to inhibit EMT, indicating that INHBB may suppress the AR and migratory capacity of nasopharyngeal carcinoma (NPC) cells through the TGF-β/Smads signaling pathway." (PMID 39029056, 2024).
atrial fibrillation (10 papers, 2012 to 2025). A disorder characterized by an electrocardiographic finding of a supraventricular arrhythmia characterized by the replacement of consistent P waves by rapid oscillations or fibrillatory waves that vary in size, shape and timing and are accompanied by an irregular ventricular response. "According to a recent research report, the expression level of LIPCAR in atrial fibrillation was strongly linked to the phosphorylation of TGF-β1 and Smad2/3, indicating that it controls atrial fibrosis through the TGF-β/Smad pathway." (PMID 40746847, 2025). "The qRT-PCR data showed an increase in gene expression for genes involved in fibrosis pathways (TGFb and SMAD-2) and extracellular matrix production (Collagen-1, Collagen-3, and Fibronectin) in patients who developed postoperative atrial fibrillation." (PMID 38892223, 2024). "In our previous work, MFGE8 suppressed atrial fibrosis via TGF‐β1/Smad2/3 pathway in an integrinβ3‐dependent way and attenuated the vulnerability to atrial fibrillation." (PMID 32945126, 2020).
breast tumors (10 papers, 2012 to 2023). "During breast tumorigenesis it seemed necessary to turn off TGF-β-mediated Smad2 responses while retaining the Smad3 responses for further progression of breast tumors of triple negative type." (PMID 31798766, 2019). "We found that 80% to 100% of the migratory tumor cells showed nuclear accumulation of Smad2/3 compared with only about 20% to 30% of the average primary tumor in all three breast tumors tested." (PMID 23113900, 2012). "Indeed, SMAD2 and SMAD4 are closely linked on chromosome 18q21, and therefore, in most breast tumors where one gene shows hemizygous loss, the other is also reduced to hemizygosity." (PMID 34475389, 2021). "We last examined whether there is a correlation between TGFβR1/Smad2 expression and tumor infiltrated macrophages in human breast tumors." (PMID 32724475, 2020). "Thus, pharmacological inhibition of TKRI activity inhibits TGF-β/Smad2 signalling of transplanted breast tumour cells in zebrafish and inhibits their invasiveness." (PMID 24196484, 2013). "Silencing of HS6ST2 reduced the transcriptional activity mediated by Smad2/3/4, thereby inhibiting the production of IL-11 induced by TGF-β, resulting in the inhibition of breast tumor growth." (PMID 37932473, 2023). "Patient samples were used to detect the phosphorylated Smad2 (the activated form of Smad2) and CD68 (a pan-macrophage marker) in breast tumor tissue using immunofluorescence staining." (PMID 32724475, 2020). "TGFβ1 treatment induced the phosphorylation of Smad2/3, which in turn, led to upregulation of miR-21 in both breast tumor cell lines; whereas SSA reduced miR-21 expression through inhibition of Smad2/3 phosphorylation." (PMID 26769851, 2016). "TrkB is capable of binding to SMAD2, SMAD3, and SMAD4 in TrkB-expressing human breast tumors." (PMID 32340410, 2020). "In this study, we found that SSA could mimic the inhibitory effect of SB-431542 on phosphorylation of Smad2/3 in both MCF-7 and MDA-MB-231 breast tumor cells." (PMID 26769851, 2016). "Our results show that SSA treatment at non-cytotoxic concentrations can specifically reduce breast tumor cell motility without influencing tumor cell growth, and the mechanism of action involves the suppression of TGFβ signaling by directly blocking Smad2/3 phosphorylation." (PMID 26769851, 2016). "In addition, the expression levels of p-Smad2, p-Smad3, and Smad4 in the nucleus of MCF-7 breast tumor cells were measured by immunofluorescence microscopy, and we found that SSA could reduce the level of p-Smad2/3 in the nucleus with or without the presence of TGFβ1." (PMID 26769851, 2016).
Loeys-Dietz syndrome (10 papers, 2017 to 2025). Loeys-Dietz syndrome is a rare genetic connective tissue disorder characterized by a broad spectrum of craniofacial, vascular and skeletal manifestations with four genetic subtypes described forming a clinical continuum. "Ultrarare damaging variants in PKD1, a gene causing autosomal dominant polycystic kidney disease, and SMAD2, a gene causing Loeys-Dietz syndrome, were associated with IA in the general population, even in the absence of a diagnosis of these disorders." (PMID 40172005, 2025). "Similarly, mutations in Tgfβ2 and Tgfβr1 cause microretrognathia in Loeys-Dietz syndrome, mutations in Tgfβr2 and Smad2 cause jaw length defects, and TGFβ signaling has been shown to be essential for patterning the proximal portion of the murine dentary." (PMID 35666955, 2022). "Finally, we did not consider genes encoding TGF-beta ligands TGFB2 and TGFB3, or SMAD2, although these were described recently to contribute to Loeys-Dietz syndrome." (PMID 31795342, 2019). "Among the genes queried, COL3A1 and aggregated testing of Loeys-Dietz syndrome-associated genes (TGFBR1, TGFBR2, SMAD2, SMAD3, TGFB2, TGFB3) were the leading signals of enrichment, consistent with prior studies [21•, 24, 25]." (PMID 37979122, 2023). "TGFBR1/2 and SMAD2/3 encode proteins involved in TGF-β signaling and mutations in these genes cause Loeys-Dietz syndrome (LDS) in patients (TGFBR1; LDS1; MIM 609192, TGFBR2; LDS2; MIM 61068, SMAD2; LDS6; MIM 619656, SMAD3; LDS3 (AOS); MIM 613795)." (PMID 35492343, 2022). "Apart from the acquired condition, inherent conditions like genetic disorders (Marfan syndrome, Loeys-Dietz syndrome, etc.)or tremendous nonsyndromic gene mutation (ATCA2, SMAD2, etc.)are associated with AD." (PMID 35178459, 2022). "LOF missense mutations in SMAD2 and SMAD3 causing Loeys-Dietz syndrome, another syndromic TAA form, are also located in the MH1 and MH2 domains." (PMID 28659821, 2017). "Among these, Loeys-Dietz syndrome (MIM # 609,192) shows mutations in other genes which are involved in the same pathway of FBN1 and include TGFBR1 (MIM * 190,181), TGFBR2 (MIM * 190,182), SMAD3 (MIM * 603,109), TGFB2 (MIM * 190,220), TGFB3 (MIM * 190,230) and SMAD2 (MIM * 601,366)." (PMID 39008115, 2024).
Peritoneal Fibrosis (10 papers, 2015 to 2025). Disorder characterized by a wide range of structural changes in PERITONEUM, resulting from fibrogenic or inflammatory processes. "TGF‐β acts as a central mediator of fibrosis by activating the Smad2/3 signaling cascade, which drives peritoneal fibrosis through the induction of EMT in PMCs." (PMID 41082405, 2025). "Overexpression of Smad7 by gene transfer inhibits Smad2/3 activation, reduces peritoneal fibrosis, and improves impaired peritoneal function in the model." (PMID 39201294, 2024). "Increased Smad2/3 activation and decreased Smad7 expression is found in a peritoneal fibrosis model exposed to PD solution containing high concentrations of glucose in uremic rats." (PMID 39201294, 2024). "Similarly, Smad2 deletion in the peritoneum exacerbates peritoneal fibrosis induced by continuous ambulatory peritoneal dialysis, indicating that Smad2 plays a suppressive role." (PMID 38569937, 2024). "In our previous study, we reported that blockade of IL-6 trans-signaling could attenuate peritoneal fibrosis by inhibiting the activation of Smad2/3, with reduced expressions of α-smooth muscle actin (α-SMA) and collagen type I (Col I) in a mouse model." (PMID 36035388, 2022). "Interestingly, transfer of Smad7 gene by ultrasound microbubble method into the peritoneum inhibits Smad2/3 activation, decreases α-SMA expression, and attenuates peritoneal fibrosis in a rat model of PD." (PMID 25885904, 2015).
Sepsis (10 papers, 2015 to 2024). Sepsis is defined as life-threatening organ dysfunction caused by a dysregulated host response to infection. "This study aimed to investigate the role of autophagy and the Smad2/3 signaling pathway in Dex-mediated treatment of sepsis-induced lung injury." (PMID 38419889, 2024). "Dex exerts its beneficial effects against sepsis-induced lung injury through the regulation of autophagy and the Smad2/3 signaling pathway." (PMID 38419889, 2024). "The TGFBR2/Smad2 signaling pathway has a critical role in LPS-induced sepsis." (PMID 39057685, 2024). "Additionally, a negative correlation between miR-149 expression and Smad2 production was observed in vitro, suggesting the critical role of Smad2 in sepsis-induced ALI." (PMID 35700140, 2022). "The putative binding site between miR-149 and Smad2 was found using the TargetScan database and indicated that has_circ_0003091 exerted its regulatory function by sponging miR-149 and subsequently affecting the Smad2 expression in sepsis-induced ALI." (PMID 35700140, 2022). "TGFBR2 overexpression aggravates LPS-induced sepsis through up-regulating Smad2/3." (PMID 35264055, 2022). "Additionally, mmu_circ_0015268 silencing ameliorated sepsis-induced the production of proinflammatory cytokines, cell apoptosis, and endothelial activation via the miR-149/Smad2 axis." (PMID 35700140, 2022). "Autophagy and the Smad2/3 signaling pathway play important roles in sepsis-induced lung injury, but the relationship between Dex and Smad2/3 is not clear." (PMID 38419889, 2024). "During sepsis, active TGF-β1 is released and attached to its receptor (TGFβI/II) resulting in the phosphorylation and activation for Smad2/3, which binds with Smad4, leading to the formation of an active complex of Smad2/3/4." (PMID 38926458, 2024).
aneurysm (9 papers, 2009 to 2022). Bulging or ballooning in an area of an artery secondary to arterial wall weakening. "In the present study, we have reconfirmed these Marfan syndrome-like phenotypes, including elastic layer disruption, aorta elongation, and aneurysm formation in the presence of increased Smad2 phosphorylation when LRP1 is deficient in the SMCs." (PMID 19742316, 2009). "To date, 9 (likely) pathogenic variants in SMAD2 have now been described in 15 subjects displaying a broad range of features, including aneurysms, tortuosity of the entire arterial tree, and coronary artery dissections, even in the absence of prominent connective tissue characteristics." (PMID 31569402, 2019). "Studies on the pathogenesis behind aortic aneurysms in Marfan syndrome and individuals with bicuspid aortic valves indicate a role of SMAD2 in aneurysm development." (PMID 27687697, 2016). "The activation of SMAD2 in the nucleus as indicated by the phosphorylated SMAD2 also significantly increased in the aneurysms of Smad3−/− mice using the antibody recognizing phosphorylated SMAD2/3." (PMID 25985281, 2015). "Furthermore, pSMAD2 positively correlated with medial TGFß ligand concentration, suggesting that SMAD2-dependent TGFß signaling plays a role in TAV aneurysm development." (PMID 36104385, 2022). "TGFß signaling through SMAD2/SMAD3 contributes to aortic remodeling in TAV, whereas TGFß-independent activation of SMAD3 may underlie aneurysm formation in BAV/UAV aortas." (PMID 36104385, 2022). "The opposite effects of SMC-specific Notch1 haploinsufficiency on Smad2 and Smad3 indicate that the crosstalk between Notch1 and Tgf-β signaling pathway in aneurysm may have differential effects on the downstream targets." (PMID 28562688, 2017). "Nonetheless, a well-documented molecular feature of syndromic aneurysm tissue from humans and genetically engineered mice is evidence for paradoxical, hyperactivated canonical TGFβ signaling in smooth muscle cells, as determined by immunostaining for phosphorylated SMAD2/3 (pSMAD2/3)." (PMID 35098309, 2022). "Indeed the underlying molecular mechanisms of the intricate interplay of TGF-β, SMAD2, SMAD3 and SMAD4 in the pathogenesis of aneurysm remains to be determined." (PMID 25985281, 2015).
aortic aneurysm (9 papers, 2015 to 2025). A ruptured aneurysm located in the wall of the proximal portion of the descending aorta proceeding from the arch of the aorta. "TβRIIb mutations result in TGF-β2 dependent increased SMAD2 phosphorylation, which is involved in aortic aneurysm progression." (PMID 26607280, 2015). "Loss-of-function mutations or deficiency of SMAD2, SMAD3, and SMAD4 genes in mice or humans lead to the formation of aortic aneurysms or dissections, suggesting that basal TGF-βsignaling canonical signaling is indispensable for maintaining the integrity of aortic structure and function." (PMID 35517795, 2022). "Down-regulation of aortic PAR-2, Smad2/3 phosphorylation and MMP-2, and reduced monocyte/macrophage infiltration were demonstrated in a mouse model of aortic aneurysm following administration of the anticoagulant fondaparinux." (PMID 28220880, 2017). "In addition, non-syndromic forms of aortic aneurysms also exhibit increased vascular TGF-β expression and SMAD-2 phosphorylation." (PMID 34827608, 2021). "While inhibition of noncanonical TGF‐β signaling ameliorates aortic aneurysm progression in MFS mice, our iPSC–SMC model showed hyperactivation of noncanonical ERK1/2 signaling and reduced Smad2 activity in response to TGF‐β in patient‐derived SMCs." (PMID 41497804, 2025).
chronic kidney disease (9 papers, 2013 to 2025). Impairment of the renal function secondary to chronic kidney damage persisting for three or more months. "In contrast, Bacteroides plebeius supplementation can counteract sarcopenia caused by chronic kidney disease through the Mystn/ActRIIB/SMAD2 pathway." (PMID 39006102, 2024). "Western blotting showed that treatment with Bacteroides plebeius reduced the expression of MSTN, SMAD2 and ACVR2B, and these expression levels were increased in rats with chronic renal failure‐associated protein depletion." (PMID 36458537, 2022). "Notably, Regulation of nuclear SMAD2/3 signaling, a pathway with direct implication in chronic kidney disease, was prioritized at the very top of the meta-analysis significant results." (PMID 33945541, 2021). "In patients with chronic kidney disease (CKD) and the fibrotic kidneys of animal models, Smad2 and Smad3 are highly active." (PMID 36835428, 2023). "It blocks the interaction between Smad2/3-TGF β RI proteins and inhibits Smad2/3 phosphorylation, thereby inhibiting RAS the TGF - β/Smad pathway, ultimately leading to the treatment of chronic kidney disease." (PMID 40098611, 2025). "This was examined in vivo in a transgenic model of TGF‐β1‐induced chronic kidney disease with Smad3 or without Smad3 expression and in vitro in mesangial cells and glomerular endothelial cells with Smad2/3 inhibitors or Smad3‐knockdown." (PMID 24744860, 2013).
colitis (9 papers, 2015 to 2025). Inflammation of the colon. "We observed that pharmacological MRA by spironolactone decreased colonic TGF-β1 production and its associated SMAD2 signaling in chronic DSS-induced colitis mice." (PMID 40634309, 2025). "Subsequently, by investigating the AOM/DSS mouse model and examining the Smad2/3 phosphorylation profiles, we clarified that carcinogenic pSmad3L-Ser signaling triggered by chronic colitis is a key early event in colitis-associated CRC." (PMID 37511456, 2023). "Furthermore, SMAD2-deficient CD4 T cells were unable to initiate colitis in a RAG adoptive transfer model and in a C. rodentium model of infectious colitis." (PMID 29910812, 2018). "Smad2/Smad3 double deficient mice develop fatal inflammatory diseases with reduction in Foxp3 expression in CD4+ T cells while Smad2 deficiency make mice susceptible to DSS induced colitis." (PMID 28003811, 2016). "Here, we show that Smad4 deprivation enhances the expression of TGF‐β1 and YAP, and YAP in turn interacts with Smad2/3 and exacerbates the development of colitis and CAC." (PMID 37261975, 2023). "Blockade of SMAD7 activity with an anti-sense oligonucleotide enhanced SMAD2 activation and reduced inflammatory cytokine production in intestinal explants and severity of colitis in mice sensitized and treated with TNBS or oxazolone." (PMID 29910812, 2018). "Conversely, I-Evs with high expression of TGF-β1 activate Smad2/3 and contribute to the upregulation of TGF-β1, thereby alleviating C. difficile TcdB-induced local colon inflammation in mice." (PMID 35967466, 2022).
Marfan syndrome (9 papers, 2009 to 2025). A disorder of the connective tissue. "AT1R and TGF-β signaling are considered detrimental in Marfan syndrome; therefore we also investigated activation of its downstream transcription factor Smad2 in the aortic root." (PMID 25238161, 2014). "TGFβ signaling is abnormally elevated in the absence of LRP1 in vivo, where analysis of SMC-specific LRP1 knockout (smLRP1−/−) mice revealed a Marfan syndrome-like phenotype with nuclear accumulation of phosphorylated Smad2 (p-Smad2) and disruption of elastic layers in the vessel wall." (PMID 19742316, 2009). "Causative genes include autosomal polycystic kidney disease (PKD1, PKD2), Ehlers–Danlos syndrome (COL3A1), Marfan syndrome (FBN1), Loeys–Dietz syndrome (TGFB2, TGFB3, TGFBR1, TGFBR2, SMAD2, SMAD3), and Majewski Osteodysplastic Primordial Dwarfism (PCNT)." (PMID 40004483, 2025).